MIR631 (microRNA 631)
Synonyms: hsa-mir-631; MIRN631
Gene: MicroRNA gene on chromosome 15 (75,353,611 to 75,353,685, reverse strand). Ensembl gene ENSG00000284343.
Gene Ontology:
Biological process: miRNA-mediated post-transcriptional gene silencing
Cellular component: RISC complex
Homologues: Orthologues: macaque mml-mir-631 (99% identical), chimpanzee ptr-mir-631 (97% identical), dog MIR631 (64% identical).